LIX1L (limb and CNS expressed 1 like)
Synonyms: MGC46719
Tractability: PROTAC: ubiquitination databases record sites on it; its protein half-life has been measured.
Gene: Protein-coding gene on chromosome 1 (145,933,423 to 145,958,017, reverse strand). Ensembl gene ENSG00000271601.
Subcellular location (Human Protein Atlas): Cytosol
Gene Ontology:
Biological process: autophagosome maturation
Cellular component: cytoplasm
Genetic constraint (gnomAD): Loss-of-function variants: 12 observed, 20.17 expected, observed/expected ratio (o/e) 0.59, 90% interval 0.38 to 0.96. The upper end of that interval is the gene's LOEUF score, 0.96, which puts it in group 4 of 6, group 1 being the genes least tolerant of losing a copy. Missense variants: 318 observed, 305.78 expected, observed/expected ratio (o/e) 1.04, 90% interval 0.95 to 1.14. Synonymous variants: 140 observed, 129.19 expected, observed/expected ratio (o/e) 1.08, 90% interval 0.94 to 1.25.
Homologues: Orthologues: chimpanzee LIX1L (100% identical), macaque LIX1L (99% identical), dog LIX1L (99% identical), pig LIX1L (99% identical), guinea pig LIX1L (98% identical), mouse Lix1l (97% identical), rat Lix1l (97% identical), rabbit LIX1L (90% identical), tropical clawed frog lix1l (84% identical), Drosophila melanogaster lft (54% identical). Paralogues in human: LIX1 (45% identical), EPG5 (28% identical).
Diseases named in the same sentence as LIX1L in open-access papers:
LIX1L is named in the same sentence as 17 diseases in open-access papers, as found by Europe PMC text mining. Sharing a sentence is not in itself a finding about the gene and the disease. The quoted sentences say what the papers report.
gastric cancer (2 papers, 2015 to 2024). A primary or metastatic malignant neoplasm involving the stomach. "To examine the functional importance of LIX1L expression in cancer cells, we first examined the effects of LIX1L knockdown on gastric cancer cell proliferation." (PMID 26310847, 2015). "OCUM-1 gastric cancer cells were transfected with LIX1L shRNA-#1 or -#2, and the effects of the LIX1L knockdown on OCUM-1 proliferation were assessed over 72 h of culture, starting from day 3 post-transfection." (PMID 26310847, 2015). "We further examined the effects of LIX1L knockdown on gastric cancer cell proliferation through a flow cytometric analysis of the effects of LIX1L on cell cycle distribution." (PMID 26310847, 2015). "LIX1L knockdown also induced apoptosis in other gastric cancer cell lines (KATO-III and MKN45) according to a caspase activity assay (data not shown)." (PMID 26310847, 2015). "Moreover, LIX1L knockdown in other gastric cancer cell lines (KATO-III and MKN45) similarly reduced proliferation (data not shown)." (PMID 26310847, 2015). "Similarly, in other gastric cancer cell lines (KATO-III and MKN45), LIX1L knockdown also suppressed BrdU incorporation and induced caspase-3/7 and −9 activities (data not shown)." (PMID 26310847, 2015).
lung carcinoma (2 papers, 2015 to 2024). "LIX1L was confirmed to be overexpressed in protein extracts from frozen surgical specimens (gastric, colon, and lung cancer)." (PMID 26310847, 2015).
bladder cancer (1 paper, 2024). "The results unequivocally demonstrate that edited miR-154-p13-5p exerts a substantial inhibitory influence on proliferation, migration, and induces apoptosis by specifically targeting LIX1L in bladder cancer." (PMID 38911375, 2024).
liver cancer (1 paper, 2024). An epithelial or non-epithelial malignant neoplasm that arises from the liver. "In the liver cancer, LIX1L interacts with miR-21-3p, upregulating its expression, which in turn targets and suppresses FBP1 expression, ultimately enhancing glucose consumption and lactic acid production." (PMID 38911375, 2024).
pancreatic cancer (1 paper, 2015). "We found that the gene and protein expression of LIX1L is increased in esophageal, gastric, breast, lung, thyroid, ovarian, kidney, liver, colon, prostate and pancreatic cancer cells." (PMID 26310847, 2015).
tumor (5 papers, 2015 to 2024). "An investigation of the mechanism(s) by which the LIX1L protein promotes cancer cell proliferation has highlighted the presence of common pathways shared among different tumor types." (PMID 26310847, 2015). "Because LIX1L promotes cancer cell proliferation, in the present study, we investigated the expression and function of LIX1L in vitro and examined the effects of this protein on in vivo tumor growth." (PMID 26310847, 2015). "LIX1L was also more strongly expressed in tumor tissues than in normal tissues." (PMID 26310847, 2015). "Therefore, the discovery of an inhibitor of LIX1L, such as shRNA, homeodomain peptides and inhibitors of specific ROS1 kinases would be useful to identify potential tumor-specific drugs for LIX1L-expressing cancer cells." (PMID 26310847, 2015). "LIX1-like protein (LIX1L) promotes miR-21–3p, inhibits FBP1, reduces lactic acid production, and affects sugar metabolism to inhibit tumor growth." (PMID 35004688, 2021). "Among these 20 common genes, the expression levels of CDK20, AKAP7, AZIN2, LIX1L, OSCP1, and SLFN12 were upregulated, while HLF was downregulated in TC-PD-L1+ tumours (Pattern 3 and Pattern 4)." (PMID 29921949, 2018). "Moreover, we identified LIX1L-targeting tyrosine kinases and LIX1-mediated miRNA expression, showing that LIX1L PY136 induced tumor cell apoptosis." (PMID 26310847, 2015).
cancer (2 papers, 2015 to 2024). A tumor composed of atypical neoplastic, often pleomorphic cells that invade other tissues. "By using TIMER2.0, we analyzed the correlation between DCHS1 and LIX1L in human cancer and found that DCHS1 expression was significantly positively correlated with LIX1L in pan-cancer." (PMID 39123216, 2024). "In the present study, we revealed that LIX1L led to common changes in cancer cells, such as signaling activation." (PMID 26310847, 2015). "To investigate the biological function of LIX1L in cancer cells, we first assessed LIX1L phosphorylation in human embryo kidney (HEK)-293 (HEK-293) cells." (PMID 26310847, 2015). "We showed that PY136 inhibited cancer cell proliferation by inhibiting the phosphorylation of Tyr136 of the LIX1L protein in vitro and in vivo, and ROS1 phosphorylated LIX1L protein to result in cell proliferation." (PMID 26310847, 2015). "Interestingly, both the knockdown of LIX1L using shRNA and the reduction of phosphorylated LIX1L using PY136 peptide inhibited cancer cell proliferation in vitro and in vivo and decreased phosphorylated Cofilin." (PMID 26310847, 2015). "Next, we examined the inhibition of LIX1L function in cancer cells." (PMID 26310847, 2015). "Initially, to determine whether LIX1L affects protein phosphorylation and assess whether this protein is involved in cancer cell proliferation, the protein spots were visualized using Pro-Q Diamond phosphoprotein gel staining." (PMID 26310847, 2015). "LIX1L is expressed in various cancer tissues and cancer cell lines." (PMID 26310847, 2015). "Thus, the results of the present study showed that LIX1L and the modifying kinase, ROS1, can be exploited as potential targets in LIX1L-expressing cancers." (PMID 26310847, 2015). "These miRNA-mRNA target analyses suggests the coordinated interplay between several miRNAs in the regulation of target genes that might play a role in the LIX1L-mediated cell proliferation, and the roles of these genes in cancer cells require further validation." (PMID 26310847, 2015). "Therefore, we hypothesized that the phosphorylation of LIX1L would play an important role in the activities of this protein in cancer cells." (PMID 26310847, 2015). "In the present study, we demonstrated that the LIX1L protein is preferentially expressed in human cancer cells, regardless of the cancer type, and therefore this protein could be targeted for therapeutic effects in a wide range of cancer types." (PMID 26310847, 2015). "LIX1L might affect Cofilin phosphorylation to promote cancer cell proliferation." (PMID 26310847, 2015). "Herein, we report the characterization of Limb expression 1-like, (LIX1L), a putative RNA-binding protein (RBP) containing a double-stranded RNA binding motif, which is highly expressed in various cancer tissues." (PMID 26310847, 2015). "However, the biological functions of the LIX1L gene, located on chromosome 1q21.1, have not been described, and little is known regarding the expression and role of this protein in cancer cells." (PMID 26310847, 2015). "The findings of the present study provide the first evidence of an altered miRNA profile for LIX1L-expressing HEK293 cells and differentially expressed miRNAs, which, if validated in future studies, might be essential in the pathogenesis of LIX1L-expressing cancer cells." (PMID 26310847, 2015).
LIX1L also shares sentences with these, for which no sentence is quoted: hepatocellular carcinoma (2 papers); breast carcinoma (1); colon cancer (1); esophageal cancer (1); Hepatic fibrosis (1); ovarian carcinoma (1); prostate carcinoma (1); renal carcinoma (1); Thrombocytopenia (1); thyroid cancer (1).